PPARG (peroxisome proliferator activated receptor gamma)
Diseases named in the same sentence as PPARG in open-access papers (continued):
Sharing a sentence is not in itself a finding about the gene and the disease.
Obesity (continued). "In other words, Pparγ has been shown to promote hepatic steatosis under the pathophysiological conditions of diet-induced obesity." (PMID 36013467, 2022). "PPARγ is a key transcription factor for adipocyte function that presents decreased expression and activity in obesity." (PMID 35624758, 2022). "Specifically, the secreted SPP1 and the nuclear PPARγ and FTO were included among the down modulated genes associated to severe obesity pathway after PBMCs treatment with EVOO, while ADIPOQ was up regulated." (PMID 36386923, 2022). "A recent study also shows that SCFAs-induced protection against HFD-induced obesity is mediated by down-regulation of PPARγ, promoting a switch from lipid synthesis to lipid oxidation." (PMID 35281054, 2022). "PPARγ acetylation, on the other hand, is commonly observed in obesity, diabetes, and aging, all of which are conditions accompanied by macrophage activation." (PMID 37213714, 2022). "Extracts of copperleaf ameliorate obesity by reducing PPARγ and C/EBPα expression in a high-fat diet mouse model." (PMID 36290616, 2022). "PPARα mainly mediates energy homeostasis, PPARβ/δ activation promotes fatty acid metabolism, and PPARγ is a dominant regulator of obesity and insulin resistance." (PMID 35473936, 2022). "Mediated by the cyclin-dependent kinase 5 (CDK5), phosphorylation of PPARγ can significantly reduce insulin sensitivity and induce obesity." (PMID 36551260, 2022). "For example, adipocyte-derived exosomes containing miR-27a were internalized by C2C12 skeletal muscle cells and via repression of PPARγ and its downstream genes seem to be related to insulin resistance induced by obesity." (PMID 36016863, 2022). "Taken together, our data suggested that FE and BFE prevented HFD-induced obesity by inhibiting adipocyte differentiation and lipogenesis, which was potentially mediated via the PPARγ signaling pathway." (PMID 36364945, 2022). "We have shown that the obesity-protective alleles (MC4R T and PPARG C) were positively associated with weight loss efficiency." (PMID 35292917, 2022). "One explanation is that the glucose lowering action of pioglitazone is mediated by ligand binding to nuclear receptor PPARG which are most abundant in adipocytes and hence greater in people with obesity." (PMID 36699039, 2022). "On the other hand, amorfrutins block HFD-induced PPARγ Ser273 phosphorylation in mouse adipocytes, leading to dysregulation of a large number of genes whose expression is altered in obesity." (PMID 35769384, 2022). "Synthetic, nonactivating PPARγ ligands can abolish the phosphorylation of PPARγ at Ser273, a posttranslational modification correlated with obesity and insulin resistance." (PMID 34339734, 2021). "In order to investigate the underlying mechanism for the anti-obesity effect of AAL, the expression levels of PPARγ and C/EBPα in differentiated 3T3-L1 cells were studied by using qPCR and Western blot." (PMID 33776618, 2021). "The induction of Pparγ expression by the small molecule harmine improves insulin sensitivity with little effect on weight gain, suggesting that inducing Pparγ expression can be used against obesity related insulin dysfunctions." (PMID 33804020, 2021). "In the other study, the authors observed that apigenin ameliorated the insulin resistance, metabolic abnormalities and obesity-related inflammation by also acting on PPARγ." (PMID 34679777, 2021). "We also sought to determine if the AGE/RAGE/DIAPH1 axis is linked to markers of adipogenesis (PPARG & PPARGC1A) and metabolic genes that we previously identified to be regulated by RAGE in a mouse model of obesity (UCP1 and CIDEA)." (PMID 34103691, 2021). "Cdk5 was the initial candidate for phosphorylating Ser273 of PPARγ based on the observation that in obesity, increased expression of Cdk5 was observed in adipose tissue, as well as higher levels of pPPARγ." (PMID 34339734, 2021).
Obesity (continued). "There is a well-studied correlation between high levels of PPARγ phosphorylated at Ser273 with increased obesity and insulin resistance." (PMID 34339734, 2021). "Following stimulation by IL6, Arid5a further represses Pparγ expression, which ameliorates adipogenesis and obesity." (PMID 35126382, 2021). "Pharmacological activators of PPARγ are being used as a treatment of obesity related disorders such as dyslipidaemia and type 2 diabetes, but questions remain open regarding the effects of PPARγ on traits related to the development of type 2 diabetes." (PMID 34887761, 2021). "Results across studies vary, however, as it has also been shown that increasing PPARγ expression suppresses ghrelin mRNA expression and thus reduces appetite and obesity." (PMID 33964966, 2021). "PPARγ also regulate several metabolic diseases, such as obesity, diabetes, inflammatory diseases and neuroinflammatory disease." (PMID 33467433, 2021). "The AMPK and PPARγ activation have been considered as alternative important targets for the treatment of T2D and obesity in recent years." (PMID 33641315, 2021). "PPARγ activation attenuated obesity-induced arterial stiffening and reduced the inflammatory and oxidative status of PVAT." (PMID 33781257, 2021). "Our findings define PPARγ as a mediator of adipocyte Nprc gene expression and establish a new connection between PPARγ and the control of adipocyte NP signaling in obesity." (PMID 34245781, 2021). "The potential of reducing BW and improving insulin sensitivity suggests a possible clinical role of PPARγ antagonists in treating obesity and type 2 diabetes." (PMID 34128467, 2021). "One putative link between obesity and global IR is how adipocytes expand their fat storage ability, an ability orchestrated by PPARγ." (PMID 33926085, 2021). "Collectively, galectin-1 exacerbates obesity of mice fed HFD by increment of PPARγ expression and activation." (PMID 33431823, 2021). "In sum, our results lead us to conclude that obesity increases Nprc expression in the adipose tissue through a PPARγ-dependent mechanism, the effect of which is the suppression of NP signaling, decreased energy expenditure, and impaired glucose homeostasis." (PMID 34245781, 2021). "In summary, the anti-obesity effects of rhein were considered to be related with the involvement of ERs, inflammation, oxidative stress, PPARγ, and INSR." (PMID 34516329, 2021). "In conclusion, our current study demonstrates that PPARγ regulates Nprc expression in adipocytes through its long-range distal enhancers, and the diet-dependent increase in Nprc expression in obesity is potentially mediated by the actions of PPARγ." (PMID 34245781, 2021). "On the other hand, peroxisome proliferator-activated receptor gamma (PPARG) is upregulated in diabetes, obesity, and MAFLD." (PMID 35087844, 2021). "The clinical features that were determined to be important for prediction included the maternal PPARγ genotypes, primiparity, number of pregnancies, obesity, BMI, and education." (PMID 34685423, 2021). "Previous human and animal studies have demonstrated that telmisartan, an ARB and a partial agonist of peroxisome proliferator-activated receptor gamma (PPAR-γ), can improve obesity related cardiometabolic sequels in obesity hypertension." (PMID 33761942, 2021). "Compared to agonists, researchers have identified only a few natural compounds that inhibit PPARγ, all of which have a moderate binding affinity for PPARγ receptor and can inhibit adipogenesis, obesity, and/or hepatic steatosis." (PMID 34128467, 2021). "Insulin sensitivity, early obesity, and PPARγ expression were assessed in CD24 knockout (KO) mice and compared to wild-type (WT) mice." (PMID 33467499, 2021). "Obesity increases expression of iNOS, which catalyzes NO synthesis and contributes to metabolic deregulation in adipocytes as well as stimulation of PPARγ expression." (PMID 33430086, 2021).
Obesity (continued). "Although hepatic expression of PPARγ is upregulated under certain pathophysiologic conditions, such as diabetes, obesity, and high-fat diet, the mechanisms leading to this induction are still to be revealed." (PMID 34072832, 2021). "PPARγ is the primary regulator of adipogenesis and lipogenesis in mammals and birds, and plays important roles in the development of obesity, the pathology of diabetes, atherosclerosis, and cancer." (PMID 32810939, 2021). "In obesity, PPARγ activation diminishes ectopic lipid accumulation, reduces inflammation, and improves insulin sensitivity and lipid metabolism." (PMID 33536069, 2021). "Several potential obesity candidate genes and variants have been documented, including LEP and LEPR, which have been mainly implicated in monogenic obesity, as well as FTO, APOE, PPARG, and PPARA which have been mainly implicated in polygenic/common obesity." (PMID 34131278, 2021). "The expression of Mogat1 in the liver has been shown to remarkably increase in high-fat diet fed mice models, and its expression is induced by obesity through direct activation of PPARγ." (PMID 34835949, 2021). "We thus proposed that pioglitazone improves PVAT microenvironments and aortic stiffening in obesity via multiple PPARγ target genes in the cells, such as macrophages and fibroblasts, residing within the PVAT." (PMID 33781257, 2021). "For example, Arid5a binds to the promoter of Pparγ to suppress transcription, which leads to inhibition of adipogenesis and obesity and to lncRNA-AU021063 to augment invasion and metastasis in breast cancer." (PMID 35126382, 2021). "It is suggested that BBR can act as a selective PPARγ activator and is expected to be a new therapeutic strategy for obesity and metabolic diseases." (PMID 34421358, 2021). "In obese HFD-induced mice, kaempferol protected against obesity and ameliorated hyperlipidemia partly through maintaining microbial diversity and modulating microbial communities as well as downregulating PPARγ and SREBP-1C." (PMID 34371900, 2021). "The naturally occurring PPARγΔ5 isoforms impair the adipogenic potential of adipocyte precursor cells by dominant-negative inhibition of PPARγ, which possibly contributes to adipose tissue dysfunction in obesity." (PMID 33716977, 2021). "The possible beneficial effect of favoring adipocyte differentiation in the treatment of obesity was in part already suggested by the positive outcome on insulin resistance of PPARγ agonists, which act, among others, by promoting adipogenesis." (PMID 32157317, 2021). "Another study showed that PPARγ deficiency protected mice from HFD-induced adipocyte hypertrophy, obesity, and IR." (PMID 33926085, 2021). "Furthermore, evidence from studies of VCE-004.8 concludes that it acts on PPARγ (peroxisome proliferator-activated receptor gamma) as a partial agonist but lacks adipogenic activity reducing the metabolic disruption and inflammatory processes that are associated with obesity." (PMID 33892826, 2021). "Considering the close connection between metabolic gene polymorphisms and obesity, the possibility that these targets (e.g., MC4R, FTO, PPARγ) in obese patients are more directly related to severe COVID-19 than BMI cannot be excluded." (PMID 34373739, 2021). "In the endothelial cell migration category, PPARG was hypermethylated in SAT, and VAT, and it was associated with obesity, indicating an important role of this gene in the reorganization of ECM." (PMID 33803198, 2021). "In the present study, we investigated the effect of an angiotensin receptor blocker (ARB) and a peroxisome proliferator activated receptor gamma (PPAR-γ) partial agonist; telmisartan, on diet induced obesity hypertension." (PMID 33761942, 2021). "The PPARγ agonist pioglitazone was used to examine the influence of PPARγ on the PVAT microenvironment and the aortic stiffening associated with obesity." (PMID 33781257, 2021).
Obesity (continued). "The function of PPARγ and its transcriptional partners in adipogenesis and their inseparable relationship with obesity and T2DM has become the target of research for future potential drug discoveries." (PMID 33926085, 2021). "In a recent report, a milk fat globule membrane (MFGM) supplement significantly reduced obesity by suppressing the PPARγ and C/EBPα proteins and mRNA expression and activating the AMPK pathway." (PMID 34064117, 2021). "PRPF8 expression recovery upon PRPF8-pcDNA3.1 transfection increased the expression of several PPARG isoforms (PPARG-2, PPARG-3, PPARG-4, and γORF4) to control levels (i.e. SC preadipocytes in NG obesity), especially in IR preadipocytes." (PMID 34545810, 2021). "The major mechanism through which obesogens can contribute to obesity is believed to be the activation of peroxisome proliferator-activated receptor gamma (PPARγ) and its heterodimeric partner, the 9-cis retinoic acid receptor (RXR)." (PMID 34940640, 2021). "Although there are probably additional factors to control Nprc gene expression, our data provide the first insights on Nprc transcriptional regulation and establish a new role for PPARγ to control adipocyte NP signaling and metabolism during obesity." (PMID 34245781, 2021). "PPARγ is a common factor shared by metabolically unhealthy obesity and impaired placental development in obese patients or in non-overweight and non-obese patients with impaired fat metabolism." (PMID 34884974, 2021). "Given the substantial role of NPRC for the control of NP signaling, our study provides a new connection to PPARγ for modulating NP signaling and energy metabolism during obesity." (PMID 34245781, 2021). "EAW attenuated HFD-induced obesity by down-regulating C/EBPα, PPARγ, and SREBP-1c to suppress adipogenesis." (PMID 34199426, 2021). "PPARγ is implicated in the pathology of numerous diseases involving cancer and obesity, and altered expressions of miRNAs, such as let-7, miR-27, and miR-143 have been found to regulate the expression and activity of PPARγ." (PMID 34552867, 2021). "Elevated PPARG activity is related to a higher incidence of obesity and impaired insulin signaling, two contributing factors to AD." (PMID 33920138, 2021). "Diet-induced obesity and/or IR induce a decline in the expression of PPARγ, with potential relevance in obesity-related cancers." (PMID 34199293, 2021). "In contrast to the well-established roles of PPARα and PPARγ in obesity, diabetes, and NAFLD, little is known about PPAR-β/δ despite its ubiquitous expression." (PMID 33926085, 2021). "This experiment proved that obesity can permanently affect PPARγ activity, a disorder that exacerbates inflammation and hypoxia, which, in turn, stimulate epigenetic changes." (PMID 34884974, 2021). "Pparγ is a major regulator of adipogenesis and obesity, and its increased expression is responsible for weight gain in animals and humans." (PMID 35126382, 2021). "Under conditions of nutrient overload and obesity, PPARγ is induced and activated in the liver, where it is involved in fatty acid storage as lipid droplets." (PMID 34069390, 2021). "In human adipose tissue, the expression of PDK1/2 was positively correlated with that of the adipogenic marker PPARγ and inversely correlated with obesity." (PMID 34552205, 2021). "In an in vivo study, a significant decrease in PPARα and PPARγ mRNA expression levels in adipose tissue was observed after 10 days of exposure to mercuric chloride (HgCl2) in high-fat diet-induced obesity in mice." (PMID 34678938, 2021). "Under conditions of nutrient overload and obesity, PPARγ is induced and activated in liver where it is involved in FA storage as lipid droplets." (PMID 32192216, 2020). "Our findings reveal the ability of UP to reduce the occurrence of obesity through increased browning of white adipose tissue via increased AMPKα, PPARγ, PGC-1α, and UCP-1 expression." (PMID 33425000, 2020).
Obesity (continued). "In obesity, phosphorylation of PPARγ at Ser273 (pSer273) by cyclin-dependent kinase 5 (CDK5)/extracellular signal-regulated kinase (ERK) orchestrates diabetic gene reprogramming via dysregulation of specific gene expression." (PMID 32024237, 2020). "In fact, TZDs activation of PPARγ not only enhances adipogenesis but also reduces fat deposition in tissues, and attenuates the inflammatory cytokines release in obesity." (PMID 33282920, 2020). "According to reports, LBP can upregulate osteoblasts activity to promote its growth; besides, it suppresses the activity of peroxisome proliferator-activated receptor (PPARγ) and reduces fat production to improve obesity." (PMID 33447177, 2020). "Investigating the molecular mechanisms that control PPARγ expression is critical for understanding adipogenesis, as well as pathological conditions such as obesity and diabetes." (PMID 32184808, 2020). "Obesogens increase obesity through a variety of potential mechanisms, including the activation of peroxisome proliferator-activated receptor gamma (PPARγ), a key regulator of adipogenesis." (PMID 32340264, 2020). "In the initial stages, PPARG balances the detrimental effects of cancer and obesity and is fully functioning." (PMID 32813759, 2020). "PPARG regulates lipid and glucose metabolism, and downregulation of PPARG has been shown to have anti-obesity effects." (PMID 31044373, 2020). "Our results indicate that ginsenoside Rb1 can promote lipid transport and ameliorate obesity by upregulating AQP7 through the PPARγ pathway." (PMID 32821266, 2020). "In old male GWAT, the mRNA levels of Pparγ and Pgc1α involved in oxidative metabolism were downregulated with obesity and with ADRB3 stimulation." (PMID 31983693, 2020). "The candidate genes were fat mass and obesity-associated (FTO), KCNJ11, potassium voltage-gated channel subfamily Q member 1 (KCNQ1), PDK4, PDX-1, paternally expressed gene-3 (PEG3), PPARG, and stearoyl-coenzyme A desaturase-1 (SCD1)." (PMID 32653024, 2020). "Thus, activation of PPARγ by autophagy can be a mechanism by which autophagy induces obesity and it could be a feasible target to prevent autophagy associated with obesity during MetS." (PMID 32015340, 2020). "Additional work is needed to determine the role of mesenchymal cell PPARγ in the bone changes seen in diabetes, obesity, and high fat diet." (PMID 33048436, 2020). "So far, intensive study of PPARγ has concentrated on its regulatory role in inflammation, atherosclerosis, insulin resistance, glucose metabolism, obesity, and tumor formation." (PMID 33281727, 2020). "In summary, our current study uses syngeneic melanoma mouse models to show that pharmacologic inhibition of PPARγ boosts anticancer immunotherapies in a sexually dimorphic and obesity-dependent manner." (PMID 32226299, 2020). "Previous studies have reported that Ser273 phosphorylation of PPARγ LBD is related to obesity-induced development of insulin resistance." (PMID 33329381, 2020). "On the other hand, activation of the AMPK pathway, a key sensor and regulator of cellular energy, inhibits adipogenesis, in part by blocking the expression of PPARγ in experimental models of obesity." (PMID 32294890, 2020). "PPARγ has a major role in the differentiation of preadipocytes into adipocytes involved in obesity development." (PMID 33297378, 2020). "PPAR regulation is not fully understood, but it is known that PPARγ mRNA expression is negatively influenced by a fasting state or long-term hypocaloric diet, while it is positively affected by obesity and high fat diets with a high ratio of fatty acids." (PMID 32536865, 2020). "Between then, an important anti-obesity activity of seaweeds is the inhibition of peroxisome proliferator-activated receptor γ (PPARγ) expression and activation of the adenosine monophosphate-activated protein kinase (AMPK) phosphorylation." (PMID 32102343, 2020).